MYO1C (myosin IC)
Description:
Myosins are actin-based motor molecules with ATPase activity. Unconventional myosins serve in intracellular movements. Their highly divergent tails are presumed to bind to membranous compartments, which would be moved relative to actin filaments. Involved in glucose transporter recycling in response to insulin by regulating movement of intracellular GLUT4-containing vesicles to the plasma membrane. Component of the hair cell's (the sensory cells of the inner ear) adaptation-motor complex. Acts as a mediator of adaptation of mechanoelectrical transduction in stereocilia of vestibular hair cells. Binds phosphoinositides and links the actin cytoskeleton to cellular membranes. [Isoform 3]: Involved in regulation of transcription. Associated with transcriptional active ribosomal genes. Appears to cooperate with the WICH chromatin-remodeling complex to facilitate transcription. Necessary for the formation of the first phosphodiester bond during transcription initiation.
Synonyms: MMI-beta; MMIb; myr2; NMI; MyoIC
Tractability: Small molecule: a structure with a bound ligand is known. Antibody: its Gene Ontology location is reachable by antibodies, with high confidence; the Human Protein Atlas places it where antibodies can reach. PROTAC: ubiquitination databases record sites on it; its protein half-life has been measured.
Gene: Protein-coding gene on chromosome 17 (1,464,186 to 1,492,698, reverse strand). Ensembl gene ENSG00000197879.
Subcellular location: Cytoplasm; Nucleus; Cytoplasm, cell cortex; Cell projection, stereocilium membrane; Cytoplasmic vesicle; Cell projection, ruffle membrane; Nucleus, nucleoplasm (Isoform 3); Nucleus, nucleolus
Subcellular location (Human Protein Atlas): Nuclear bodies; Plasma membrane
Pathways (Reactome):
Sensory Perception: Sensory processing of sound by inner hair cells of the cochlea; Sensory processing of sound by outer hair cells of the cochlea
Disease: FCGR3A-mediated phagocytosis
Gene expression (Transcription): B-WICH complex positively regulates rRNA expression
Immune System: Regulation of actin dynamics for phagocytic cup formation
Vesicle-mediated transport: Translocation of SLC2A4 (GLUT4) to the plasma membrane
Gene Ontology:
Molecular function: protein binding; signaling receptor binding; small GTPase binding; actin filament binding; ATP binding; cytoskeletal motor activity
Biological process: positive regulation of cell migration; protein targeting to membrane; regulation of bicellular tight junction assembly; vascular endothelial growth factor signaling pathway; actin filament-based movement; endocytosis
Cellular component: basal plasma membrane; cytoplasm; extracellular exosome; filamentous actin; lateral plasma membrane; membrane; membrane raft; microvillus; nuclear body; nucleus; plasma membrane; stress fiber; actin cytoskeleton; cytoplasmic vesicle; cytosol; nucleoplasm; unconventional myosin complex; actin filament; cell cortex; myosin complex; nucleolus; plasma membrane bounded cell projection; ruffle membrane; stereocilium membrane
Genetic constraint (gnomAD): Loss-of-function variants: 102 observed, 144.87 expected, observed/expected ratio (o/e) 0.7, 90% interval 0.6 to 0.83. The upper end of that interval is the gene's LOEUF score, 0.83, which puts it in group 3 of 6, group 1 being the genes least tolerant of losing a copy. Missense variants: 1,460 observed, 1,427.8 expected, observed/expected ratio (o/e) 1.02, 90% interval 0.98 to 1.07. Synonymous variants: 643 observed, 569.87 expected, observed/expected ratio (o/e) 1.13, 90% interval 1.06 to 1.2.
Gene-disease validity (ClinGen):
ClinGen rates the evidence that MYO1C causes each of these diseases.
nonsyndromic genetic hearing loss (autosomal dominant): Disputed.
Homologues: Orthologues: chimpanzee MYO1C (99% identical), pig MYO1C (98% identical), rat Myo1c (97% identical), mouse Myo1c (97% identical), guinea pig MYO1C (97% identical), dog MYO1C (95% identical), macaque MYO1C (95% identical), rabbit MYO1C (92% identical), tropical clawed frog myo1c (78% identical), zebrafish myo1cb (72% identical). Paralogues in human: MYO1H (59% identical), MYO1B (43% identical), MYO1A (41% identical), MYO1D (39% identical), MYO1G (38% identical), MYO7A (33% identical), MYO7B (33% identical), MYH2 (31% identical), MYH6 (31% identical), MYH7 (31% identical), MYH7B (31% identical), MYH3 (31% identical), and 32 more.
Diseases named in the same sentence as MYO1C in open-access papers:
MYO1C is named in the same sentence as 39 diseases in open-access papers, as found by Europe PMC text mining. Sharing a sentence is not in itself a finding about the gene and the disease. The quoted sentences say what the papers report.
prostate carcinoma (7 papers, 2014 to 2022). A carcinoma that arises from epithelial cells of the prostate gland. "MMP9 plays a significant role in prostate cancer progression and is secreted in association with the motor protein myosin IC, whose nucleocytoplasmic distribution in prostate cancer cells is regulated by calcium." (PMID 29921791, 2018). "Our results add to this picture by highlighting how, in prostate cancer cells, palmitic acid determines the exosome-associated content of the metastatic progression marker and exosomal secretion molecule caveolin 1 and prostate cancer-associated exosomal motor protein myosin IC." (PMID 32545453, 2020). "This possibility is suggestive when juxtaposed with the most recently characterized mechanism of exosome secretion in prostate cancer cells, which implicated the aggressive prostate cancer-specific isoform A of myosin IC in the secretion of MMP-containing exosomes." (PMID 29921791, 2018). "While myosin IC controls unimpeded cell migration, the advanced prostate cancer-specific isoform A of this motor protein controls invasion by promoting the secretion of exosomes containing matrix metalloproteases." (PMID 32545453, 2020). "We recently found that in prostate cancer cells, free (unimpeded) migration and invasion across the reconstituted extracellular matrix are controlled differently by isoforms of myosin IC." (PMID 32545453, 2020). "The tumor-suppressor qualities of myosin IC have recently been characterized in non-prostate-cancer cells." (PMID 29671777, 2018). "MYO1CA, an isoform of MYO1C, is involved in prostate cancer cell migration and it has been speculated that alterations of MYO1C at the plasma membrane might affect the metastatic potential of tumour cells." (PMID 31443305, 2019). "Following the discovery of the NLS within the IQ domain of myosin IC that mediates the interaction with apo-calmodulin, it was demonstrated that in prostate cancer cells, elevation of the intracellular calcium concentration drives the nuclear import of this myosin." (PMID 29671777, 2018). "While the data show that myosin IC is involved in prostate cancer cell migration, migration outside extracellular matrix in vitro proves little affected specifically by isoform A. Nevertheless, this isoform stimulates invasion through extracellular matrix, pointing to a critical role in secretion." (PMID 28814772, 2017). "Nonetheless, we reasoned that myosin IC and specifically isoform A may be involved in the migration of prostate cancer cells out of the primary tumor." (PMID 28814772, 2017). "Since calmodulin, acting as the light chain, modulates the motor properties of myosin IC and itself undergoes nuclear import via the facilitated pathway, it appears promising to investigate next the intranuclear calcium regulation of the myosin functions in prostate cancer." (PMID 29671777, 2018). "Furthermore, the data demonstrate that myosin IC is involved in prostate cancer cell migration." (PMID 28814772, 2017).
gastric cancer (5 papers, 2017 to 2021). A primary or metastatic malignant neoplasm involving the stomach. "MYO1C controls nuclear membrane tension has been previously reported as recurrently deleted in gastric cancer and is thought to have a role in PIK3 signalling." (PMID 33632293, 2021). "MiR-137 was also found to play a tumor-suppressive role in gastric cancer cell lines via interacting with Kruppel like factor 12 and myosin IC." (PMID 29016699, 2017). "In addition, miR-137 targets KLF12 and MYO1c in gastric cancers to inhibit tumorigenesis." (PMID 34539732, 2021). "Several studies had showed that Myosin 1 C (MYO1C) may play a key role in regulatingautophagosome–lysosome fusion through F-actin remodeling, and miR-137 overexpression inhibited the cell migration, proliferation by targeting Krűppel-likefactor 12 (KLF12) and MYO1C in gastric cancer cell lines." (PMID 34488531, 2021).
deafness (3 papers, 2016 to 2024). An inherited or acquired condition characterized by the complete loss of the ability to hear from one or both ears. "Although inherited mutations in MYO1C have been described for deafness in humans and mice, MYO1C’s role in cytoskeletal development, similar to that of FLNB, suggests a potential mechanism for inherited lethal SNVs in stillbirth." (PMID 36800380, 2023). "Mutations in MYO6 and MYO1C are a major cause of deafness in humans, however, so far a detailed phenotypic analysis of the affected patient families for other pathologies related to dysfunctional autophagy have not yet been performed." (PMID 27146966, 2016). "Association of MYO1C and MYO1F variants with deafness was disputed by the ClinGen Hearing Loss Clinical Domain Working Group (CDWG) due to a lack of sufficient functional analyses." (PMID 38562617, 2024). "To date, three genes encoding the class-I myosins, MYO1A, MYO1C and MYO1F, were initially reported as human “deafness genes”." (PMID 38562617, 2024).
endometrial carcinoma (3 papers, 2016 to 2021). A malignant tumor arising from the epithelium that lines the cavity of the uterine body. "We found a significant correlation between the tumor stage and lowered expression of MYO1C in endometrial carcinoma samples." (PMID 27716847, 2016). "This study was designed to examine MYO1C expression status in a panel of well-stratified endometrial carcinomas as well as to assess the biological significance of MYO1C as a tumor suppressor in vitro." (PMID 27716847, 2016). "In the present work, we examined the level of MYO1C in a panel of well-stratified endometrial carcinomas to inspect the potential correlation of MYO1C protein levels with tumor stage and prognosis." (PMID 27716847, 2016). "Although, to the best of our knowledge, no previous studies showed MYO1C being involved in cortical neuronal migration, a selection of papers reported MYO1C regulating migration in tumor cells, such as glioblastoma cells (1321 N1 cell) and endometrial carcinoma cells." (PMID 35053800, 2021). "We examined levels of MYO1C protein in a panel of well-stratified endometrial carcinomas and found a significant negative association (P = 0.035) between the level of MYO1C protein expression in hyperplasia and stage III tumors." (PMID 27716847, 2016).
glioma (3 papers, 2018 to 2024). A benign or malignant brain and spinal cord tumor that arises from glial cells (astrocytes, oligodendrocytes, ependymal cells). "Upregulated genes, such as EGFR and MYO1C, are associated with glioma cell proliferation and migration, whereas downregulated genes such as MMP11 and SREBF1 are related to cell adhesion and lipid metabolism (bottom)." (PMID 29587824, 2018). "Here, we identified an EV export mechanism for MYO1C that promotes glioma cell invasion and is dependent on RAB31 in GhECs." (PMID 37953466, 2024). "We overexpressed MYO1C in glioma cells (GCs) and glioma stem cells (GSCs) and found that it promoted their invasive ability." (PMID 37953466, 2024). "This study aimed to investigate the specific enrichment mechanism of MYO1C in GhEC‐EVs and provide a new theoretical basis for glioma treatment strategies targeting blood vessels." (PMID 37953466, 2024). "The overexpression of MYO1C in glioma EVs induced glioma cell migration, and its knockdown inhibited this effect." (PMID 39062515, 2024). "We previously isolated glioma human endothelial cells (GhECs) and found that GhECs, rather than normal human brain endothelial cells (NhECs), exhibit specific enrichment of MYO1C into EVs and promote the migration of glioma cells." (PMID 37953466, 2024). "Here, we detected MYO1C protein in cells and EVs of NhECs and GhECs (17#, 21#, 15#) from different glioma tissues." (PMID 37953466, 2024). "In summary, our data illustrate that the knockdown of RAB31 can reduce the enrichment of MYO1C in extracellular vesicles, thereby attenuating the promotion of glioma cell invasion by GhEC‐EVs." (PMID 37953466, 2024). "Knockdown of RAB31 reduces enrichment of MYO1C in extracellular vesicles, thereby attenuating promotion of glioma cell invasion by GhEC‐EVs." (PMID 37953466, 2024). "We previously demonstrated that glioma human endothelial cell (GhEC)‐EV, rather than normal human brain endothelial cell (NhEC)‐EV, promote glioma cell migration, and MYO1C in GhEC‐EVs was significantly higher than that in NhEC‐EVs." (PMID 37953466, 2024). "In summary, our data indicate that the knockdown of RAB31 can reduce enrichment of MYO1C in extracellular vesicles, thereby attenuating the promotion of glioma cell invasion by GhEC‐EVs." (PMID 37953466, 2024). "Finally, we identified an EV export mechanism for MYO1C that promotes glioma cell invasion and is dependent on RAB31 in GhECs." (PMID 37953466, 2024). "Glioma human endothelial cells (GhECs) (unlike normal human brain endothelial cells (NhECs)), exhibit specific enrichment of MYO1C into EVs." (PMID 37953466, 2024). "We identified 20 GSC-upregulated miRNA-targeted genes associated with significantly reduced 5-year survival in GBM patients, including previously identified glioma-promoting genes HMGA2, MYO1C, RGS4, and several novel targets, such as HPCAL1, IMPDH1, and YWHAG (orange-colored genes)." (PMID 29587824, 2018).
breast carcinoma (2 papers, 2019 to 2023). "An overexpression plasmid or siRNA against MYO1C were sequentially introduced into human breast cancer MDA-MB-231 cells." (PMID 31699152, 2019). "However, gene expression analysis shows that Myo1C is predominantly downregulated in several types of cancer, with ovarian cancer being the most prevalent (50% of all cancer cases have reduced expression of Myo1C), followed by the large intestine, kidney, lung, urinary tract, and breast cancers." (PMID 37816864, 2023).
glioblastoma (2 papers, 2021). The most malignant astrocytic tumor (WHO grade IV). "Indeed, Myo1c was recently found to be critical for cell migration in glioblastoma and endothelial cells." (PMID 34380438, 2021).
liver fibrosis (2 papers, 2024). "Our previous studies have reported that SWT might improve liver fibrosis by regulating the expression of Myo1c, Syde1 and Rhoj in LSECs." (PMID 39741334, 2024).
COVID-19 (1 paper, 2023). A disease caused by infection with severe acute respiratory syndrome coronavirus 2. "The results indicated six hub DEGs for comparison of T1DM and COVID-19 convalescence (CD3G, YES1, ALAS2, MYO1C, NCR3, PRKACB) and two hub DEGs for comparison of T2DM and COVID-19 convalescence (PTRF, EHD1)." (PMID 38169604, 2023).
epilepsy (1 paper, 2021). A brain disorder characterized by episodes of abnormally increased neuronal discharge resulting in transient episodes of sensory or motor neurological dysfunction, or psychic dysfunction. "Herein, we identified seven genes (NCL, SEPHS2, PA2G4, SLC35G2, MYO1C, GPR158, and POU3F1) with de novo variants but unknown pathogenicity that were not previously associated with epilepsy." (PMID 34489640, 2021).
lung carcinoma (1 paper, 2022). "Myosin IC (MYO1C) was differentially expressed in lung cancer and normal tissues." (PMID 36101745, 2022).
melanoma (1 paper, 2019). A malignant, usually aggressive tumor composed of atypical, neoplastic melanocytes. "Of note, we also checked cBioPortal and found that these proteins related to angiogenesis (i.e. FASN, CLIC4, HSPB1, ARHGEF1, PHGDH, MYO1C, CAV1) are altered in a total of 242 melanoma patients out of a total of 471 (51.36%)." (PMID 31142788, 2019).
nephrotic syndrome (1 paper, 2024). A collection of symptoms that include severe edema, proteinuria, and hypoalbuminemia; it is indicative of renal dysfunction. "We identified homozygous missense variants in MYO1C in two unrelated children with nephrotic syndrome (c.292C>T, p.R98W; c.2273 A>T, p.K758M)." (PMID 38659911, 2024). "We here identified recessive variants in MYO1C as a potential novel cause of nephrotic syndrome in children." (PMID 38659911, 2024).
Obesity (1 paper, 2015). Accumulation of substantial excess body fat. "However, 4/11 have known or potential roles in obesity, MYO1C, PLIN4, PARD3 and PDE7B." (PMID 25651499, 2015).
osteosarcoma (1 paper, 2016). A usually aggressive malignant bone-forming mesenchymal neoplasm, predominantly affecting adolescents and young adults. "Since the same PH domain is present in NM1, we prepared mutants lacking the PI-binding ability in both NM1 and Myo1c (K908A and K898A, respectively), and observed their localization in human osteosarcoma (U2OS) cells by wide-field fluorescence microscopy." (PMID 27480647, 2016).
pancreatic ductal adenocarcinoma (1 paper, 2023). An infiltrating adenocarcinoma that arises from the epithelial cells of the pancreas. "Herein, our work reported that a novel m6A-modified circRNA from the MYO1C gene, circMYO1C, upregulated in the pancreatic ductal adenocarcinoma (PDAC)." (PMID 36781839, 2023).
pulmonary fibrosis (1 paper, 2023). Chronic progressive interstitial lung disorder characterized by the replacement of the lung tissue by connective tissue, leading to progressive dyspnea, respiratory failure, or right heart failure. "The results showed that the expression of Myo1c and F-actin increased in pulmonary fibrosis in vivo and in vitro but was reduced by hucMSCs treatment." (PMID 37335082, 2023).
retinal degeneration (1 paper, 2021). Degeneration of the retina. "Since mutations or deletion of the motor protein, MYO7A, were associated with retinal degeneration in Usher syndrome and its animal model, we were prompted to investigate the effect of Myo1c in retinal function." (PMID 34073294, 2021).
Stillbirth (1 paper, 2023). Death of the fetus in utero after at least 22 weeks of gestation. "Though the study was limited in ascertaining de novo from inherited variants, due to unavailability of paternal DNA, genes were reported by the authors that are either lethal, known to cause disease, or increase stillbirth risk (e.g., CCR5, FAT1, FLNB, INPP5K, MYO1C, PLOD2)." (PMID 36800380, 2023).